AHR (aryl hydrocarbon receptor)
Diseases named in the same sentence as AHR in open-access papers (continued):
Sharing a sentence is not in itself a finding about the gene and the disease.
melanoma (84 papers, 2012 to 2026). A malignant, usually aggressive tumor composed of atypical, neoplastic melanocytes. "While several studies have associated AhR with melanoma prognosis and resistance to immune checkpoint inhibitors, significant gaps persist." (PMID 39835132, 2024). "In melanoma, AhR activation has been linked to the recruitment and activity of regulatory T cells (Tregs), which suppress anti-tumor immunity." (PMID 39835132, 2024). "In melanoma, AhR is implicated in multiple chemical carcinogenic signaling pathways and exhibits a dual role, functioning as both a promoter and suppressor of tumorigenesis." (PMID 39835132, 2024). "AhR was proposed to display tumor suppressor function in multiple cancers associated with the brain, liver, digestive system, and skin (melanoma)." (PMID 36258210, 2022). "We show here that the Aryl hydrocarbon Receptor (AhR) transcription factor directly regulates the gene expression program associated with the acquisition of resistance to BRAF inhibitor (BRAFi) in melanoma." (PMID 36305167, 2022). "Despite its role as an oncogene, AhR functions as a tumor suppressor in many cancers associated with the brain and central nervous system, liver, digestive system, skin (melanoma), and reproductive tract." (PMID 33451095, 2021). "The AhR/ARNT heterodimer upregulates cytochrome P450 expression which is associated with melanoma prognosis." (PMID 33446631, 2021). "They found that AhR expression was associated with the efficacy of MEK inhibitors in NRAS-mutant melanoma cell lines." (PMID 33451095, 2021). "To further investigate the role of the Kyn-AHR pathway in promoting cancer-associated immune suppression in a more controlled setting, we generated a pre-clinical model of B16-F10 melanoma overexpressing IDO (B16IDO) or TDO (B16TDO)." (PMID 32782249, 2020). "Conversely, AhR is constitutively activated in a subset of melanoma cells, promoting their dedifferentiation, associated with the expression of BRAFi-resistance genes." (PMID 32708687, 2020). "We thus proposed the use of AhR inhibitors to prevent the canonical AhR activity associated with dedifferentiation and the resistance phenotype during BRAFi treatment of melanoma." (PMID 32708687, 2020). "Silencing of AHR via the introduction of targeting small hairpin RNAs resulted in growth deficiency in AHR-high human melanoma cell lines, IPC-298, and SK-MEL-2." (PMID 31795255, 2019). "In support of this notion, genome-wide association studies more recently identified AHR as a susceptibility locus, which is involved in both the skin pigmentation/decreased tanning response and increased risk for melanoma." (PMID 31795255, 2019). "In an AhR deficient background, increased Aldh1a1 activity likely supports primary tumorigenesis and lung metastasis of melanoma cells, whereas a reduction in Aldh1a1 activity impaired the pro-tumorigenic effects caused by AhR depletion." (PMID 26242870, 2015). "The tumorigenic potential of sh-AhR melanoma cells was found to be associated with an increase in the pool of cancer stem-like cells." (PMID 26242870, 2015). "For instance, although AHR is implicated in the recruitment of immunosuppressive cells, the key downstream targets of the AhR pathway in melanoma, their roles in shaping the tumor microenvironment, and their potential as reliable prognostic markers have yet to be fully characterized." (PMID 39835132, 2024). "The loss or inhibition of the AhR significantly reduced migration capacity of melanoma cells." (PMID 36305167, 2022). "Together this underlines AhR‐induced genomic and non‐genomic reprogramming of melanoma cells." (PMID 36305167, 2022).
melanoma (continued). "AhR might act as tumor suppressor regarding melanoma cells, as its activity was associated with decreased migration and invasion, a reduced numbers of cancer stem-like cells, and aberrant β1-integrin and caveolin 1 concentrations." (PMID 33499346, 2021). "Although AhR activation by BRAFi induces an expression program associated with the sensitive/differentiate state of melanoma cells, canonical activation of AhR switches cells to an expression program associated with the resistant/dedifferentiated/invasive state." (PMID 32708687, 2020). "Indeed, AHR is a susceptibility gene for squamous cell carcinoma and a prognostic factor for melanoma and Merkel cell carcinoma." (PMID 31552251, 2019). "We, and others, have also established an association between AhR and melanoma." (PMID 26242870, 2015). "Aldh1a1 overactivation in an AhR-deficient background enhances melanoma progression." (PMID 26242870, 2015). "Collectively, these findings position AhR as a central node linking metabolic plasticity to ferroptosis vulnerability, offering a novel axis for therapeutic intervention in drug-resistant melanoma." (PMID 41872128, 2026). "In melanoma, the probiotic Lactobacillus reuteri releases I3A, activating AhR in CD8+ T cells to produce IFN‐γ, enhancing immune checkpoint inhibitor efficacy and prolonging progression‐free survival (PFS) and overall survival (OS)." (PMID 40103267, 2025). "The overexpression of IDO in melanoma tumors led to an increase in the expression of AHR on TI-Treg and an improvement in their suppressive capabilities." (PMID 39950085, 2025). "This study provides significant insights into the role of the AhR pathway in melanoma, particularly in relation to tumor progression and immune modulation." (PMID 39835132, 2024). "Although these studies demonstrate an oncogenic role for AhR, there are also some reports indicating that AhR has a tumor suppressive role in melanoma." (PMID 38807762, 2024). "Recent evidences in melanoma, where AhR appears to promote macrophage polarization towards immunosuppressive phenotype and widely suppress immune cell function, complicating its utility as a straightforward therapeutic target." (PMID 39835132, 2024). "These analyses aim to uncover potential therapeutic strategies for melanoma by targeting key molecules in the AHR, MAP2K1, KLF5, PRKACB, and PIK3R2 signaling pathways." (PMID 39835132, 2024). "A more profound understanding of the molecular mechanisms linking AHR with melanoma is evidently required." (PMID 39835132, 2024). "These analyses aim to identify therapeutic strategies for melanoma by targeting key genes (AHR, MAP2K1, KLF5, PRKACB, PIK3R2) and their regulatory RNA networks, offering potential for personalized treatments and novel biomarkers to improve clinical outcomes." (PMID 39835132, 2024). "Recent work has shown that AhR drives resistance to BRAF inhibitors in melanoma, and that AhR inhibition with resveratrol and flavinoids re-sensitize melanoma to BRAF inhibition." (PMID 38807762, 2024). "By enhancing our understanding of the AhR pathway, this research provides a foundation for identifying new treatment strategies and clarifying the biological mechanisms driving melanoma progression." (PMID 39835132, 2024). "Immunohistochemistry revealed that human melanoma patient samples express lower levels of AhR compared to human nevi." (PMID 38807762, 2024). "Kyn indeed binds the aryl hydrocarbon receptor (AhR) which upregulates the expression of genes involved in immune suppression and in melanoma progression." (PMID 38794128, 2024). "This study provides an integrated approach to understanding the AhR pathway’s role in melanoma, identifying MAP2K1, PRKACB, KLF5, and PIK3R2 as critical prognostic markers and therapeutic targets." (PMID 39835132, 2024). "The Aryl Hydrocarbon Receptor (AhR) pathway significantly influences immune cell regulation, impacting the effectiveness of immunotherapy and patient outcomes in melanoma." (PMID 39835132, 2024).
melanoma (continued). "Overactivation of AhR signaling has been detected in several cancer types, including melanoma and cutaneous squamous cell carcinoma." (PMID 38361944, 2024). "An examination of the expression profiles of melanoma patients from the TCGA database, compared to normal controls from the GTEx database, revealed that AHR, MAP2K1, and PRKACB were upregulated in melanoma, whereas KLF5 and PIK3R2 were downregulated." (PMID 39835132, 2024). "Melanoma cells expressing a constitutively active AhR were found to have reduced tumorigenicity in either genetic background." (PMID 37106727, 2023). "In melanoma cells, the knockdown of AhR’s expression resulted in increased expression of the stem cell marker ALDH1a1, and the increased ALDH1a1 was found to drive enhanced invasion, migration, and tumorigenecity." (PMID 37106727, 2023). "Significantly, syngeneic C57BL/6J mice transplanted intra-cutaneously with AhR knockout-HCmel12 melanoma cells exhibited a substantial reduction in the frequency and number of pulmonary metastases." (PMID 37830596, 2023). "We previously found that the anti-inflammatory drug leflunomide had AhR-dependent antiproliferative effects in melanoma cells." (PMID 37106727, 2023). "We demonstrated that the Aryl hydrocarbon Receptor (AhR) transcription factor is constitutively activated in a subset of melanoma cells, promoting the dedifferentiation of melanoma cells and the expression of BRAFi‐resistant genes." (PMID 36305167, 2022). "Overall, these results report that AhR mediates specific gene signature controlling the phenotypic switch of melanoma cells." (PMID 36305167, 2022). "Herein, we aimed to delineate the role of AhR in orchestrating melanoma phenotypic switching during the acquisition of resistance through genomic and non‐genomic routes." (PMID 36305167, 2022). "AhR is markedly expressed in highly dedifferentiated, resistant, and invasive melanoma cells, mediating resistance to BRAFi." (PMID 36305167, 2022). "Accordingly, genetic depletion of AhR in BRAFi‐resistant SKMel28 melanoma cells (SK28R) by CRISPR Cas9 technology (AhR KO; Fig EV1A) significantly reduced their resistance to various BRAFi (vemurafenib, dabrafenib, and encorafenib)." (PMID 36305167, 2022). "We previously showed in a preclinical PDX melanoma mice model that antagonizing AhR delayed the emergence of resistant cells." (PMID 36305167, 2022). "We determined that the A375 melanoma cells used in this study expressed lower overall levels of AhR than A431 squamous cell carcinoma cells." (PMID 35169210, 2022). "When AHR-KO melanoma cells have been transplanted into immunocompetent mice, local growth and metastatic dissemination were decreased, suggesting a functional role of AHR in cancer induced-inflammation." (PMID 36497228, 2022). "This study reports that the AhR/SRC axis constitutes a therapeutic vulnerability in BRAFi‐resistant melanoma." (PMID 36305167, 2022). "It warrants future clinical studies targeting the AhR‐dependent SRC/FAK/EGFR axis in combination with BRAFi/MEKi double blockade to re‐sensitize melanoma to standard melanoma treatment and counteract resistance." (PMID 36305167, 2022). "With respect to VISTA, knockdown or pharmacological inhibition of the AhR reduces VISTA expression in melanoma cell lines." (PMID 36713558, 2022). "In particular, we pinpoint the crosstalk between AhR and SRC in reshaping cell fate and identify the AhR/SRC axis as a new therapeutic vulnerability for the treatment of BRAFi‐resistant melanoma." (PMID 36305167, 2022). "IDO/TDO activation-mediated kynurenine (Kyn) accumulation in the TME activates AhR, leading to T cells differentiation into FoxP3+ regulatory T cells and thus melanoma immune escape." (PMID 36003368, 2022). "The identification herein of the AhR/SRC activation loop in BRAFi‐resistant melanoma gives rationale to these studies filling an important gap to understand cell plasticity and propose innovative therapeutic regimens." (PMID 36305167, 2022).
melanoma (continued). "Correlative analysis (Das efficacy/gene expression) further showed that the SRCi Das was more effective in cell lines with a high level of AhR mRNA and strongly expressing genes mediating resistance, invasion, and melanoma dedifferentiation." (PMID 36305167, 2022). "Remarkably, through ligand‐binding interaction, AhR has the capacity to integrate environmental and cell‐dependent signals to shape and adapt the cell response, making AhR a very attractive candidate in regulating melanoma plasticity." (PMID 36305167, 2022). "AhR has also been proposed to have a tumor suppressor function in melanoma, as its knockdown promotes primary melanoma tumorigenesis and lung metastasis in mice." (PMID 33451095, 2021). "Surprisingly, there have been very few studies reported on the role of AhR in melanoma promotion and progression, although AHR is highly expressed in melanoma cell lines." (PMID 33499346, 2021). "Human melanoma cell lines with the highest protein level of AhR have also inhibited migration and invasion activity." (PMID 33499346, 2021). "It was reported that although AHR expression in the tumor inhibits melanoma growth and metastasis, the expression of this receptor in the stroma promotes melanomagenesis." (PMID 33499346, 2021). "We previously reported that activated AhR reprograms the transcriptome of melanoma cells mediating BRAFi resistance." (PMID 33724679, 2021). "In melanoma, AhR agonists, for example, can activate the AhR-dependent resistant program to induce dedifferentiation, whereas AhR antagonists can abrogate deleterious AhR sustained-activation to overcome dedifferentiation and drug resistance." (PMID 35002727, 2021). "It is supposed that tumor progression and metastasis depend on stromal AhR in the case of AHR knockdown in melanoma cells." (PMID 33499346, 2021). "We recently showed that a sustained AhR activation promotes the dedifferentiation of melanoma cells and the expression of BRAFi‐resistance genes." (PMID 33724679, 2021). "On the other hand, it was reported that environmental chemicals considered as AhR agonists contribute to melanoma progression and invasion through the stimulation and activity of MMPs." (PMID 33499346, 2021). "It is well known that AhR dimerizes with ARNT to trigger melanoma progression, but ARNT also fulfills its multiple functions in tumorigenesis by cooperating with bHLH-PAS family members." (PMID 33446631, 2021). "We recently reported that the Aryl hydrocarbon Receptor (AhR), a ligand‐dependent transcription factor is an upstream central node regulating the expression of BRAFi‐resistance genes and melanoma dedifferentiation." (PMID 33724679, 2021). "Among them, we focus on the role of natural flavonoids to control AhR transcriptional activity and their function in melanoma treatment." (PMID 32708687, 2020). "The use of BRAFi combined with these flavonoids, which counteract canonical AhR activity, avoids the emergence of the BRAFi-resistant cells responsible for melanoma relapse." (PMID 32708687, 2020). "Despite the high similarity of the structures between the flavonoids, their function on AhR and especially melanoma-cell survival under BRAFi treatment was significantly different." (PMID 32708687, 2020). "We recently demonstrated that in melanoma, BRAFi constitute a new class of aryl hydrocarbon receptor (AhR) transcription factor ligands that promote sensitivity by triggering a transcriptomic program associated with cell differentiation." (PMID 32708687, 2020). "Targeting of AhR with antagonists was suggested as a strategy for delaying the relapse during the treatment of melanoma with vemurafenib or for inhibiting constitutive AhR activity in prostate cancer." (PMID 32316498, 2020). "We recently showed the involvement of AhR transcription factor in the acquisition of resistance during melanoma treatment by BRAFi." (PMID 32708687, 2020).
melanoma (continued). "We recently involved the canonical activation of AhR transcription factor in the acquisition of resistance during BRAFi treatment of melanoma." (PMID 32708687, 2020). "FICZ has a high affinity to the aryl hydrocarbon receptor (AhR) and activates AhR response genes, including cyclooxygenase-2 (Cox2), a melanoma prognostic marker gene, and cytochrome P4501A1, which increases ROS accumulation." (PMID 31252639, 2019). "Experiments with B16 melanoma cells and tumor transplantation studies in mice indicated that AHR has anti-tumorigenic properties in tumor cells but pro-tumorigenic functions in the tumor stroma." (PMID 31795255, 2019). "In different experimental melanoma models, making use of cell culture approaches and in vivo models, it was shown that AHR activation can modulate several central hallmarks of cancer." (PMID 31795255, 2019). "Collectively, these results demonstrate that laquinimod improves the effector functions of AhR-competent NK cells against B16F10 melanoma cells." (PMID 30808363, 2019). "In the following sections, we introduce recent findings regarding how AHR contributes to the maintenance of skin cancers, mainly focusing on melanoma." (PMID 31552251, 2019). "For malignant melanoma, AHR’s role is less clear, which emphasizes the urgent need for additional mechanistic and clinical-oriented studies, for instance, assessing AHR’s impact on DNA repair, apoptosis, and respective consequences for melanoma initiation." (PMID 31795255, 2019). "Here, we provide evidence that the aryl hydrocarbon receptor-dependent activation of NK cells is relevant for the efficacy of laquinimod to suppress melanoma cell metastases and CNS autoimmunity." (PMID 30808363, 2019). "Here, the authors show that the Aryl hydrocarbon Receptor (AhR) is a key mediator of resistant genes and use resveratrol, an AhR antagonist, to revert resistance in melanoma bearing mice." (PMID 30429474, 2018). "Our data also highlight the potential of AhR antagonists as sensitizers of melanoma-targeted therapy." (PMID 30429474, 2018). "Having established that AhR-signatures discriminate cell differentiation states and sensitivity/resistance to BRAFi, we explored these AhR signatures in melanoma samples." (PMID 30429474, 2018). "In this study, we established an important role of AhR transcription factor in controlling sensitivity or resistance to BRAFi in melanoma." (PMID 30429474, 2018). "Again, the appearance of the α-signature co-occurred with the resistance signature and dedifferentiation process, as observed in melanoma cell lines, supporting these AhR-dependent activation programs." (PMID 30429474, 2018). "We also demonstrated that AhR constitutes a therapeutic target to delay relapse during the treatment of melanoma by BRAFi and thus merits to be tested in human." (PMID 30429474, 2018). "The AhR is also constitutively active in prostate cancer, melanoma, ovarian cancer, colon cancer, and gastric cancer." (PMID 29487603, 2018). "Here, we mainly focus on the potential role of AhR transcription factor in resistance mechanisms occurring during melanoma treatment by BRAFi." (PMID 30429474, 2018). "Here, we demonstrate that the Aryl hydrocarbon Receptor (AhR) transcription factor is constitutively activated in a subset of melanoma cells, promoting the dedifferentiation of melanoma cells and the expression of BRAFi-resistance genes." (PMID 30429474, 2018). "Although more work is needed to clarify this differential pattern of expression, it agrees with our previous observations describing cell-autonomous and stromal dependent functions of AhR in melanoma primary tumorigenesis and metastasis." (PMID 28874739, 2017).